FANCD2 (FA complementation group D2)
Diseases named in the same sentence as FANCD2 in open-access papers (continued):
Sharing a sentence is not in itself a finding about the gene and the disease.
Fanconi anemia (continued). "Curcumin increases the apoptotic effects of cisplatin on cisplatin-resistant lung adenocarcinoma cells by inhibiting FANCD2 monoubiquitination and, therefore, also preventing activation of the Fanconi anemia/BRCA pathway that enables DNA repair by homologous recombination." (PMID 33330091, 2020). "Moreover, exons 14 and 15 coding region is also recognized by FANCD2 (Fanconi anemia group D2) protein, which binds to the BRCA2 protein between codons 2350 and 2545." (PMID 31191615, 2019). "We also show that in absence of a functional Dicer or Drosha, the assembly into nuclear foci of the Fanconi anemia (FA) protein FANCD2 and of the replication and checkpoint factor TopBP1 in response to replication stress is impaired, and the activation of the S-phase checkpoint is defective." (PMID 31320994, 2019). "However, the MMC sensitivity observed in sgSWS1 and sgSWSAP1 cells is modest compared with disruption of members of the Fanconi anemia pathway such as FANCD2 and is comparable to what is observed in Swsap1−/− mouse fibroblasts." (PMID 31665741, 2019). "Interestingly, we also identified many proteins from the Fanconi Anemia core complex, which are important for the activity of the FANCD2–FANCI complex upon DNA damage." (PMID 31180492, 2019). "In the Fanconi anemia pathway, deubiquitination of FANCD2 is a fundamental regulatory step." (PMID 31253762, 2019). "In addition, FANCD2, another Fanconi Anemia (FA) protein, is also required for CC formation, likely through promoting the recruitment of BLM to the replication stressed ALT telomeres." (PMID 31836759, 2019). "BRIP1 acts late in the Fanconi anemia pathway, after FANCD2 ubiquitination." (PMID 29483558, 2018). "FANCD2 protein belongs to the Fanconi Anemia Pathway and is required for repair of DSB and intra-S-phase checkpoint activation, while SUV39H1 is a methyltransferase that directs H3K9 methylation on large chromatin domains adjacent to the DSB to promote activation of DSB-signaling proteins." (PMID 30038706, 2018). "FANCD2/FANCI mono-ubiquitylation promotes retention of the core Fanconi anaemia complex on damaged chromatin and has been shown to be an essential step in coordinating recruitment of a number of key proteins to ICL repair sites, including the nuclease FAN1 and CtIP." (PMID 25833379, 2015). "Replication stress is known to induce DNA damage due to the stalled or collapsed forks, which then activates ATM/ATR-mediated cell cycle checkpoint responses to promote fork stability and restart thorough Rad18 and Fanconi anemia (FA) DNA repair pathways (monoubiquitinated FANCD2)." (PMID 25742788, 2015). "Similarly, the hypersensitivity of FANCD2 worms and Fanconi anemia patient cells to ICLs was rescued by inhibiting NHEJ." (PMID 25853498, 2015). "FANCD2 belongs to the Fanconi Anemia family which has at least 15 family members." (PMID 25749046, 2015). "FANCD2 is part of the Fanconi Anemia pathway that is important for DNA crosslink repair and HR." (PMID 24829461, 2014). "In our efforts to understand the molecular basis of treatment response in advanced cervical cancer, besides the BRCA pathway, we also found the fanconi anemia (FA) complementation group, FANCD2, FANCL, FANCM, FANCJ/BRIP1/BACH and FANCI, to be involved in intrinsic resistance to chemo-radiotherapy." (PMID 24708616, 2014). "Radiobiology of Fancd2−/− (Fanconi anemia) mice and bone marrow-derived cell lines." (PMID 24596683, 2014). "In addition to FANCL, GGN1 interacted with the critical component of the Fanconi Anemia (FA) pathway FANCD2 and a downstream component of the BRCA pathway, BRCC36." (PMID 23451117, 2013). "Finally, USP1 deubiquitinates and inactivates two components of DNA repair mechanisms: FANCD2 (a component of the Fanconi Anemia pathway) and PCNA." (PMID 21283576, 2011).
Fanconi anemia (continued). "The remaining third includes four genes conserved in nematodes, fly, mouse, and human (zfp-1, R11F4.1, apl-1 and fcd-2) and whose human homologs are linked to disorders (AF10/MLLT10: leukemia, Glycerol kinase: hyperglycerolemia, APP: Alzheimer's, and FANCD2: Fanconi anemia)." (PMID 18752680, 2008). "Understanding the role of FANCD2 in Fanconi anemia could lead to new treatments." (PMID 32167469, 2020). "Similarly, impairment of the DNA interstrand crosslink repair pathway, Fanconi anemia, by depletion of FANCD2 did not cause DPC accumulation compared to control cells." (PMID 27871366, 2016). "Interestingly, the p-DNA-PKcs at S2056 for non-homologous end joining and the ubiquitination of Fanconi anaemia complementation group D2 (FANCD2) for FA repair showed higher endogenous expression levels and were activated in CL1-0 cells but not in CL1-5 cells after MMC treatment." (PMID 27833080, 2016). "Given that both FANCD2 and BRCA2 mutations (in homozygous state) cause the same chromosomal instability syndrome called Fanconi anemia, it is likely that breast cancers that arise in carriers of a mutation in these genes may have similar clinical characteristics." (PMID 25093046, 2014). "Well-characterized substrates of USP1 include FANCD2 and FANCI, key components of the Fanconi anemia DNA repair pathway, as well as PCNA, which plays a central role in DNA replication and repair." (PMID 40940964, 2025). "FANCC depletion diminished the nuclear foci formation of FANCD2 upon MMC exposure, indicating a defect in the DNA damage response of the Fanconi anemia core complex." (PMID 41065314, 2025). "Further research on FANCD2 and other FANC proteins in nLDs will elucidate one of the fundamental questions in the pathophysiology of Fanconi anemia." (PMID 41065314, 2025). "USP1 also plays a critical role in DNA repair by deubiquitinating key proteins such as FANCD2 and PCNA, thereby regulating the Fanconi anemia pathway and homologous recombination." (PMID 40940964, 2025). "Studies have shown that mTOR inhibitors, such as AZD8055, can downregulate FANCD2 expression, reduce ATM/Chk2 activity, and weaken the repair capacity of the Fanconi anemia pathway, thereby exacerbating DNA damage accumulation." (PMID 40725100, 2025). "In response to DNA damage, FANCD2 and FANCI form a heterodimer – known as the ID complex – and are monoubiquitylated by the Fanconi anemia core complex." (PMID 41065314, 2025). "ICL traversal also depends on ATR and the Fanconi anemia pathway and involves, among other proteins, FANCM, FANCD2 and PRIMPOL." (PMID 39766854, 2024). "Dysregulation of genes related to NER (FANCB and FANCD2), BER (MBD4), and Fanconi anemia (FANCB and FANCD2) was also observed." (PMID 39728796, 2024). "ATR phosphorylates these sites to permit chromatin loading of the FANCD2/FANCI complex and activation of the Fanconi anemia pathway." (PMID 37392383, 2023). "In particular, treatment with bortezomib reduced the levels of Fanconi Anemia (FA) factors BRCA1/2 and FANCD2, and proved effective to induce DNA damage and cell death in combination with melphalan." (PMID 36569948, 2022). "FANCD2 and FANCI are ubiquitylated by the Fanconi anemia core complex in a site-specific manner upon recruitment to chromatin during the repair of inter-strand crosslinks." (PMID 33348378, 2021). "Localization of FANCD2, part of the FANCI-FANCD2 (ID2) binding complex in the Fanconi anaemia (FA) pathway, to sites of induced DNA damage was severely impeded in cells expressing the p.L605F isoform." (PMID 34861889, 2021). "FANCD2 and FANCI are critical proteins that are mono‐ubiquitylated as part of the activation process within the Fanconi anaemia (FA) pathway, which is required for the repair of inter‐strand crosslinks (ICLs)." (PMID 33625522, 2021).
Fanconi anemia (continued). "Deubiquitination of FANCD2 and FANCI appears to be as important as ubiquitination, in the regulation of the Fanconi Anemia pathway." (PMID 32117957, 2020). "In summary, we reported here a novel connection between a ribosomal protein and Fanconi anemia proteins, demonstrating that RPS27L binds to and stabilizes FANCD2 and FANCI." (PMID 33051438, 2020). "Here we identified that RPS27L binds to FANCD2 and FANCI, two Fanconi anemia (FA) proteins functioning in ICL repair pathway." (PMID 33051438, 2020). "Fanci and Fancd2 have common and distinct functions in mouse models of Fanconi anemia, while the double knockout of FANCI and FANCD2 has an unexpectedly distinct phenotype compared to single knockouts in human cells." (PMID 32167469, 2020). "The associations involving DNA double-strand break repair pathway and Fanconi anemia, in particular, were also evident when examining key individual genes, including BRCA1, BRCA2, FANCD2, FANCI, and RAD51." (PMID 31610796, 2019). "Among these, FANCD2, FANCI and other proteins of the Fanconi Anemia complex were highly enriched, including APITD1, also known as CENPS, which promotes mono-ubiquitination of FANCD2-FANCI in response to DNA damage." (PMID 31180492, 2019). "Another advantage for testing RAD51 and FANCD2 was that these protein foci formations require other upstream proteins, such as five RAD51 paralog proteins and eight Fanconi anemia proteins." (PMID 27257868, 2016). "USP1 regulates the mono-ubiquitination of FAND2 in the Fanconi anemia (FA) pathway, and it requires UAF1 to have deubiquitinating activity for regulation of Ub-FANCD2 deubiquitination." (PMID 26919101, 2016). "FANCL is the RING E3 subunit of the Fanconi anaemia complex, which functions with the E2 UBE2T to mono-ubiquitylate FANCD2 and FANCI following interstrand cross-link (ICL) detection, and is therefore crucial for ICL repair." (PMID 25833379, 2015). "We show that central components of the Fanconi anemia (FA) DNA repair pathway, the tumor suppressor proteins FANCI and FANCD2 (the ID complex), are SUMOylated in response to replication fork stalling." (PMID 25557546, 2015). "Moreover, we speculate that both proteins are likely to function in the Fanconi Anemia pathway as knockdown of Snm1B does not increase the sensitivity of FANCD2-deficient cells to MMC, and PSF2 interacts with the FANCF protein." (PMID 23189151, 2012). "The FANCD2 ubiquitin-dead K561R mutant, which can no longer be monoubiquitylated by the Fanconi anemia core complex, still exhibited nLD localization in the OA-supplemented medium, similar to the wild-type FANCD2." (PMID 41065314, 2025). "A genome-wide comparative analysis identified that the accelerated regions in elephants are enriched in Fanconi anemia (FA) complementation group L (FANCL), a ubiquitin E3 ligase that mediates the monoubiquitylation of FANCD2 as an essential step in the FA pathway." (PMID 40708996, 2025). "On the other hand, ssDNA gaps generated during the Fanconi Anemia response, which strongly impacts TRC resolution, may also be repaired by TLS, as FANCD2 recruits DNA polymerase η, a low fidelity polymerase enriched at actively transcribed genes." (PMID 37898641, 2023). "In healthy HSCs, NIPA plays a crucial role in DNA damage repair as a regulator of FANCD2, the key player in the Fanconi anemia pathway, rather than regulating the cell cycle itself." (PMID 35646639, 2022). "Mechanistically, we find that multiple genes in the homologous recombination and Fanconi anemia repair pathways, including BRCA1, FANCD2, and RAD51, are dependent on Wnt/β‐catenin signaling in Wnt‐high cancers, and treatment with a PORCN inhibitor creates a BRCA‐like state." (PMID 33660437, 2021). "These adverse effects can be scavenged by detoxifying enzymes, which have been the main focus of recent research in patients of a rare hereditary Fanconi anemia and animals with impaired expression of the DDR gene FANCD2 and the detoxifying enzymes ALDH2 and ADH5." (PMID 33573309, 2021).
Fanconi anemia (continued). "This approach revealed the FANCI (Fanconi anemia pathway) as a partner of FANCD2 (ferroptosis negative regulator, up) in COAD." (PMID 33670487, 2021). "Notably, we discovered VUS in the Fanconi anemia (FA) genes FANCD1, FANCD2, and FANCS in three patients." (PMID 32555368, 2020). "Compared to treatment with MMC alone, the Fancd2-Brca1 interaction and the amount of Brca1 on chromatin were decreased when cells were co-exposed to MMC and Hcy, suggesting Hcy could impair the Fanconi anemia (FA)/Brca1 pathway." (PMID 33029090, 2020). "Recent study showed that FANCD2 facilitates replication through CFSs in the absence of exogenous stress and does so independently from the Fanconi anemia (FA) core complex and monoubiquitination of FANCD2." (PMID 32166014, 2020). "Interestingly, more than half of the possible pathogenic variants identified in patients with mesothelioma were located within genes of the Fanconi anemia pathway (FANCA, FANCC, FANCD2, and FANCM)." (PMID 31263571, 2019). "It is interesting that cells from patients with Fanconi Anemia (FA, a rare disorder characterized by defects in DNA damage repair) harbor genomic amplification of EVI153, thus implicating a potential link between FANCD2 and EVI1." (PMID 31434871, 2019). "Among DNA repair genes, we detected a high presence of members of the Fanconi Anemia Complementation Group (FANCC, FANCD2, FANCG, FANCA, and FANCE), which participate in homologous recombination DNA repair, and genes involved in double-strand break repair (BRCA2, BRIP1, BARD, BLM, CHEK2, and PALB2)." (PMID 30487452, 2018). "Similar to cross link-induced FANCD2 foci, FANCD2 foci at CFSs on metaphase chromosomes colocalize with the FANCD2 binding partner FANCI and they are dependent on FANCD2 monoubiquitylation by the Fanconi Anemia core complex." (PMID 30486458, 2018). "Proteins other than BRCA2 implicated in homologous recombination or the Fanconi anemia repair pathway, like BRCA1, RAD51, PALB2, XRCC3, FANCI, or FANCD2, were at most modestly affected, as were non-homologous end joining proteins like KU80, KU70, and XRCC4." (PMID 28575672, 2017). "The central complex in this pathway is formed by the Fanconi anemia complementation group D2 (Fancd2), a core component of the Fanconi anemia complex, and FAI (FANCI) proteins forming the FANC1-FANCD2 (ID) complex that are phosphorylated by ATR (ataxia telangiectasia and Rad3-related)." (PMID 29234487, 2017). "In response to ICLs, JMJD-1.1 did not affect the focus formation of FCD-2, a homolog of FANCD2, a key protein in the Fanconi anemia pathway." (PMID 25853498, 2015). "Several proteins in the BRCA-Fanconi anemia (FA) pathway, such as FANCJ, BRCA1, and FANCD2, interact with mismatch repair (MMR) pathway factors, but the significance of this link remains unknown." (PMID 24966277, 2014). "The Fanconi anaemia (FA) pathway constitutes a central genome maintenance system that orchestrates the repair of DNA interstrand crosslinks (ICLs) through the coordinated monoubiquitination of FANCI and FANCD2, followed by recruitment of repair effectors such as BRCA1, REV1, and ERCC1." (PMID 41486508, 2026). "However, with 12 h of bortezomib treatment, we did not observe a reduction in Fanconi anaemia (FA) complementation group D2 (FANCD2) or RAD51, two factors that were depleted in multiple myeloid cells upon similar treatment." (PMID 37607592, 2023). "Moreover, monoubiquitinated FANCD2 (ub-FANCD2) is required for FANCI monoubiquitination (ub-FANCI) and recruitment of Breast Cancer 1 (BRCA1), Fanconi Anemia Complementation Group J (FANCJ), and Fanconi Anemia Complementation Group N (FANCN), to form damage-induced foci on chromatin 29,30." (PMID 33029090, 2020).
Fanconi anemia (continued). "Furthermore, radiobiologic studies in tumors bearing Fancd2−/− and FancG−/− mice may lead to the clinical translation of JP4-039/F15 as a potential radioprotectant during radiotherapy of Fanconi anemia patients, or other patients with genetic defects in DNA repair." (PMID 24596683, 2014).